LGALS3BP (galectin 3 binding protein)
Diseases named in the same sentence as LGALS3BP in open-access papers (continued):
Sharing a sentence is not in itself a finding about the gene and the disease.
chronic pancreatitis (3 papers, 2018 to 2022). A chronic inflammatory process causing damage and fibrosis of the pancreatic parenchyma. "The second report, using a spectral library-based proteomic approach, analyzed N-glycosylated peptides of various protein including LGALS3BP in a cohort consisting of patients with PDAC, chronic pancreatitis and healthy subjects." (PMID 34565385, 2021).
depression (3 papers, 2019 to 2023). "Galectin-3 binding protein (Gal3BP), sCD163, galectin-3, and depression have been linked to cardiovascular disease and mortality." (PMID 31752995, 2019).
diabetes (3 papers, 2012 to 2023). "If one considers the genes involved in the BRB, Lgals3bp has been a common gene upregulated in two mouse models of diabetes, and was potentially upregulated in this study." (PMID 22993483, 2012). "Perhaps, the gain-of-function of the Lgals3bp–Itgb1 and Fn1–Itgb1 pairs may explain the role of Hrchi fibroblasts in diabetic myocardial fibrosis." (PMID 37010266, 2023). "Galectin-3-binding protein, an AGE-binding protein, can enhance the iBRB dysfunction in diabetes and play a significant role in AGE-related pathophysiology during diabetic retinopathy." (PMID 27280065, 2016).
HIV-1 infection (3 papers, 2013 to 2023). The type species of lentivirus and the etiologic agent of acquired immunodeficiency syndrome (AIDS). "90K/LGALS3BP has been reported to be an interferon-stimulated gene that is upregulated in individuals with cancer or HIV-1 infection." (PMID 24156545, 2013). "Considering SARS-CoV-2 S contained the furin cleavage site, 90 K may recognize and interfere furin cleavage of SARS-CoV-2 S. As in the case of 90 K restricting HIV-1 infection, a direct binding verification is also needed amongst LGALS3BP/90 K, furin, and SARS-CoV-2 S in future work." (PMID 36591809, 2023).
non-small cell lung carcinoma (3 papers, 2014 to 2023). A group of at least three distinct histological types of lung cancer, including non-small cell squamous cell carcinoma, adenocarcinoma, and large cell carcinoma. "A study investigated the role of LGALS3BP expression, evaluated by IHC (Immunohistochemistry) as an adverse prognostic indicator in 72 pathological stage I non-small cell lung cancer patients." (PMID 34565385, 2021). "In addition, the concentrations of LGALS3BP was an independent prognostic factor significantly correlating with tumor histology (it was higher in sera derived from small cell lung cancer patients compared to non-small cell lung cancer patients), lymph node and distant metastases." (PMID 34565385, 2021).
systemic lupus erythematosus (3 papers, 2017 to 2025). An autoimmune multi-organ disease typically associated with vasculopathy and autoantibody production. "Galectin-3-binding protein (LGALS3BP) is highly expressed in lupus plasma EVs and is a lupus disease activity marker and a thrombus-related molecule." (PMID 41614843, 2025). "Interestingly, these studies indicate that a small set of MP-proteins, in particular, overexpression of galectin-3-binding protein (G3BP) distinguish MPs in patients with venous thromboembolism and the systemic autoimmune disease, systemic lupus erythematosus (SLE)." (PMID 28405179, 2017).
Alzheimer disease (2 papers, 2023 to 2025). A progressive, neurodegenerative disease characterized by loss of function and death of nerve cells in several areas of the brain leading to loss of cognitive function such as memory and language. "In concordance to our findings in HsAPOE4 lysosomes, LGALS3BP expression appears decreased post-in mortem in the Alzheimer disease entorhinal cortex." (PMID 41103078, 2025). "First, proteomics screening and statistical analysis show that blood biomarkers LGALS3BP, ACE, and POSTN effectively screen for cerebral amyloid depositions and clinically diagnose Alzheimer’s disease, but the theoretical basis is still lacking." (PMID 37446296, 2023).
asthma (2 papers, 2022 to 2025). "The relative expression levels of LGALS3BP were significantly increased (p < 0.05) between the healthy and asthma groups." (PMID 39858200, 2025). "Among these genes, VMP1, ZNF205, ZNF205, and LGALS3BP showed significant reductions (p < 0.05) in expression between the healthy and asthma groups." (PMID 39858200, 2025).
breast tumors (2 papers, 2012). "Positive staining for LGALS3BP antigen was observed in more than 50% of all cells in tissue sections of the most breast tumors types and non-cancerous breast tissues." (PMID 23181716, 2012).
colitis (2 papers, 2021 to 2024). Inflammation of the colon. "Here, we showed that Lgals3bp−/− mice were highly susceptible to colitis and colon tumorigenesis, accompanied by the induction of inflammatory responses." (PMID 33824294, 2021). "Overall, Lgals3bp−/− mice were highly susceptible to colitis." (PMID 33824294, 2021). "Furthermore, a decrease in LGALS3BP has been associated with a reduction of colon inflammation in a study performed in mice, suggesting its role as a potential immunotherapeutic target for colon inflammation." (PMID 38975221, 2024). "To understand the role of Lgals3bp in inflammatory responses during colitis, we measured the expression of pro-inflammatory cytokines, such as IL-6, TNF-α, and IL-β using RT-qPCR." (PMID 33824294, 2021). "Taken together, Lgals3bp plays a critical role in the suppression of colitis and colon tumorigenesis through the downregulation of the TAK1-NF-κB-cytokine axis." (PMID 33824294, 2021). "Colitis analysis was performed by monitoring the body weight; it was significantly reduced in Lgals3bp−/− mice, as compared to WT mice." (PMID 33824294, 2021). "The expression of pro-inflammatory cytokines was significantly higher in the colons of Lgals3bp−/− mice than in the colons of WT mice, and these results were consistent with those for colitis severity; this was confirmed by ELISA." (PMID 33824294, 2021).
dengue fever (2 papers, 2016 to 2021). "The aim of this study was to investigate the serum concentration and potential interaction of soluble galectin-1, galectin-3, galectin-9, galectin-3 binding protein (galectin-3BP), glycoprotein 130 (gp130), and E-, L-, and P-selectin in patients with dengue fever in acute febrile phase." (PMID 27240351, 2016).
gastric cancer (2 papers, 2021 to 2023). A primary or metastatic malignant neoplasm involving the stomach. "In this work, authors demonstrated that LGALS3BP expression was upregulated by human telomerase reverse transcriptase (hTERT), whose activity is peculiar in gastric cancer." (PMID 34565385, 2021). "Moreover, they showed that LGALS3BP was overexpressed in gastric tumors both as secreted protein and at immunohistochemical level, and it was significantly associated with distant metastases and later tumor stages, appearing to be a good prognostic marker for gastric cancer." (PMID 34565385, 2021).
invasive breast carcinoma (2 papers, 2012 to 2021). A carcinoma that infiltrates the breast parenchyma. "There are no researches to explore the function of LGALS3BP in ER+ and HER2- invasive breast cancer." (PMID 34760348, 2021).
lupus nephritis (2 papers, 2021 to 2022). Glomerulonephritis in the context of systemic lupus erythematosus. "Of interest, the galectin-3 binding protein (G3BP)+ EV and urinary high-mobility group box 1 molecule (HMGB1)+ EV seem to be involved in lupus nephritis pathogenesis." (PMID 33919576, 2021).
metastatic disease (2 papers, 2021 to 2023). "Also, a prominent role for Lgals3bp in tumor progression has been revealed, as elevated expression levels of Lgals3bp in serum and tumor tissue positively correlate with poor survival or a more advanced and/or metastatic disease, in most of the human solid cancers." (PMID 37491623, 2023).
non-alcoholic steatohepatitis (2 papers, 2017 to 2022). "In addition, LGALS3BP was recently identified as a promising biomarker for non-alcoholic steatohepatitis and pancreatitis, known obesity-related diseases." (PMID 28095459, 2017).
schizophrenia (2 papers, 2021 to 2023). A major psychotic disorder characterized by abnormalities in the perception or expression of reality. "Seven switch genes, NPAS3, ARHGAP15, LGALS3BP, DPP10, SMYD3, CPXCR1, and HLA-DRB5, were associated with known risk factors for schizophrenia." (PMID 36982982, 2023). "Likewise, NPAS3, ARHGAP15, LGALS3BP, DPP10, SMYD3, CPXCR1, and HLA-DRB5 were associated with known risk factors for schizophrenia." (PMID 36982982, 2023).
Stroke (2 papers, 2017 to 2023). Sudden impairment of blood flow to a part of the brain due to occlusion or rupture of an artery to the brain. "The aim of this study was to assess the expression patterns of serum galectin-1 (Gal-1), galectin-3 (Gal-3), galectin-9 (Gal-9), and galectin-3 binding protein (Gal-3BP) and their associations with stroke outcome in large artery atherosclerotic (LAA) stroke." (PMID 28112232, 2017). "The top five genes that were significantly upregulated in MG in the aged stroke brain included MG related genes (Lgals3, Lyz2, Lgals3bp) and another interferon-stimulated gene (ISG), Ifitm3." (PMID 36824976, 2023). "Other MG markers, such as Lgals3, Ifitm3 and Lgals3bp, were also upregulated in MG and other cells following stroke." (PMID 36824976, 2023).
venous thromboembolism (2 papers, 2017 to 2020). Occlusion of the lumen of a vein by a thrombus that has migrated from a distal site via the blood stream. "The overexpression of galectin-3-binding protein was observed in patients with venous thromboembolism and systemic autoimmune diseases." (PMID 32754043, 2020).
Autoimmunity (1 paper, 2025). The occurrence of an immune reaction against the organism's own cells or tissues. "LGALS3BP, alternatively designated as Gal3-BP, 90K, Mac2-BP, or CyCAP, is a secreted multifunctional glycoprotein that has been implicated in modulating pathological processes across infection, autoimmunity, multi-organ fibrosis, and oncogenesis." (PMID 41209003, 2025).
Azoospermia (1 paper, 2025). Absence of any measurable level of sperm,whereby spermatozoa cannot be observed even after centrifugation of the semen pellet. "Interestingly, LGALS3BP has been demonstrated to play a role in predicting successful sperm retrieval in non-obstructive azoospermia (NOA) patients." (PMID 40710106, 2025).
bladder cancer (1 paper, 2025). "In summary, findings presented here highlight LGALS3BP as a promising candidate for further investigation into its potential as a urinary biomarker and a therapeutic target for bladder cancer." (PMID 41046347, 2025). "We found a significantly elevated LGALS3BP expression in bladder cancer tissues, correlating with disease progression." (PMID 41046347, 2025). "Here, we report on a secreted glycoprotein, Galectin-3-binding protein (LGALS3BP), as a potential biomarker and therapeutic target for bladder cancer." (PMID 41046347, 2025).
choriocarcinoma (1 paper, 2022). An aggressive malignant tumor arising from trophoblastic cells. "This study aimed to analyze the effect of LGALS3BP on the effectiveness of MTX treatment in choriocarcinoma." (PMID 35038949, 2022). "Our findings suggest the potential of LGALS3BP as a useful prognostic marker and a promising therapeutic strategy for development of more effective choriocarcinoma therapies." (PMID 35038949, 2022). "The concentration of LGALS3BP was significantly elevated in serum samples from patients with MTX-resistant choriocarcinoma compare to MTX-sensitive choriocarcinoma (P < 0.01)." (PMID 35038949, 2022). "The concentration of LGALS3BP in patient serum of MTX-sensitive choriocarcinoma was 621.39 ~ 6651.35 ng/ml, and the concentration of LGALS3BP in patient serum of MTX-resistant choriocarcinoma was3376.00 ~ 10,157.90 ng/ml." (PMID 35038949, 2022). "Further study is needed to study the function and mechanism of LGALS3BP in MTX-resistance in choriocarcinoma." (PMID 35038949, 2022). "Meanwhile, the sera concentration of LGALS3BP was higher in MTX-resistant patients than MTX-sensitive patients indicating LGALS3BP may be a molecular mark to predict MTX-resistance in choriocarcinoma." (PMID 35038949, 2022). "Our data indicate that LGALS3BP contributes to MTX-resistance in choriocarcinoma." (PMID 35038949, 2022). "Moreover, knocking down of LGALS3BP can significantly reverse the resistance of MTX while overexpressing of LGALS3BP will lead to MTX-resistance in choriocarcinoma." (PMID 35038949, 2022). "In this study, we found that LGALS3BP is overexpressed not only in MTX-resistant JAR and JEG3 cells but also in serum samples from patients with MTX-resistant choriocarcinoma." (PMID 35038949, 2022). "This study focused on the relationship between LGALS3BP expression and MTX-resistance in choriocarcinoma to verify whether LGALS3BP can regulate the sensitivity of choriocarcinoma cell lines toward MTX." (PMID 35038949, 2022).
clear cell renal cell carcinoma (1 paper, 2024). "In conclusion, our study demonstrates the relationship between LGALS3BP and proliferation, stemness and angiogenesis in clear cell renal cell carcinoma and indicates that LGALS3BP may be a potential prognostic biomarker." (PMID 38393692, 2024).
coronary artery disease (1 paper, 2025). "Clinically, elevated plasma LGALS3BP levels are correlated with long-term mortality in coronary artery disease." (PMID 41209003, 2025).
fungal infection (1 paper, 2025). "Lgals3bp is associated with regulation of microglia responses to brain infection, and this might explain the extensive activation of microglia in response to the acapsular fungal infection and its early reduction from brain tissue in mice." (PMID 40038673, 2025).
intracerebral hemorrhage (1 paper, 2023). A cerebrovascular disorder characterized by bleeding into one or both cerebral hemispheres including the basal ganglia and the cerebral cortex. "Taken together, our data provide a general mechanism, intracerebral hemorrhage, and a molecular regulator, LGALS3BP, instructing a functional astrocyte subset with high therapeutic potential." (PMID 38066208, 2023).
Lewy body dementia (1 paper, 2018). A progressive form of dementia characterized by the presence of protein deposits called Lewy bodies in the midbrain and cerebral cortex, and loss of cholinergic and dopaminergic neurons. "After extensive meta-analysis, we only found alterations at mRNA level for AZGBP1 and ALPP in Parkinson’s disease, and LGALS3BP in Lewy body dementia; and thus, suggesting that the deregulated proteins identified in our study were mostly specific of AD." (PMID 29541381, 2018).
male infertility (1 paper, 2023). The inability of the male to effect fertilization of an ovum after a specified period of unprotected intercourse. "Since previous studies reported the use of LGALS3BP as a biomarker for other types of male infertility, incorporating the use of EVs as a supplement may improve the success of treatments for this type of condition." (PMID 36834494, 2023). "Interestingly, LGALS3BP has also been identified as a biomarker for male infertility." (PMID 36834494, 2023).
oligoasthenoteratozoospermia (1 paper, 2024). A form of male infertility that is characterized by a combination of low number or oligozoospermia, poor motility or asthenozoospermia, and abnormal shape or teratozoospermia of sperms. "Key proteins associated with sperm function, such as NPC intracellular cholesterol transporter 2 (NPC2), galectin-3-binding protein (LGALS3BP), lipocalin-1 (LCN1), and prolactin-inducible protein (PIP), show reduced expression in oligoasthenoteratozoospermia (OAT)." (PMID 39685846, 2024).
osteosarcoma (1 paper, 2024). A usually aggressive malignant bone-forming mesenchymal neoplasm, predominantly affecting adolescents and young adults. "Lgals3bp secreted from osteosarcoma binds the Lgals3 ligand on the surface of M1 macrophage, thereby enhancing their anti-tumor abilities." (PMID 38279161, 2024).
Pleural effusion (1 paper, 2021). The presence of an excessive amount of fluid in the pleural cavity. "Results suggested that LGALS3BP expression at serum and pleural effusions level does not have the same biological significance, in contrast with previous studies in other tumors; maybe because some tumour-specific factors could affect systemic and local expression of LGALS3BP." (PMID 34565385, 2021).
prediabetes (1 paper, 2024). "Increased levels of LGALS3BP were observed in prediabetes at both time points (P < 0.05), and the association held after adjustment for age and BMI in both cross-sectional prediabetes versus healthy comparisons." (PMID 39589852, 2024). "Interestingly, LGALS3BP, which was prediabetes associated, showed an increase over time in T2D-progressors but not in prediabetes-progressors or nonprogressors." (PMID 39589852, 2024). "The remaining 11 proteins were associated only with prediabetes and included vascular cell adhesion protein 1 (VCAM1) and galectin-3-binding protein (LGALS3BP)." (PMID 39589852, 2024).
preeclampsia (1 paper, 2022). Preeclampsia is a hypertensive disorder of pregnancy that is characterized by new-onset hypertension with proteinuria presenting after 20 weeks of gestation, and depending on mild or severe forms may initially present with severe headache, visual disturbances, and hyperreflexia. "This study shares similarities to ours as we have observed increased LGALS3BP mRNA expression with increased inflammation, indicating the possible involvement of galectin-3BP in inflammation associated with preeclampsia." (PMID 36311252, 2022). "Given inflammation and placental hypoxia play crucial role in pathophysiology of preeclampsia, we examined the effect of pro-inflammatory cytokines (IL-6 and TNFα) and hypoxia on LGALS3 and LGALS3BP mRNA expression in placental cytotrophoblast and syncytiotrophoblast cells." (PMID 36311252, 2022).
progeria (1 paper, 2025). "Our findings underscore the pivotal role of fibroblasts in aortic progeria-associated vascular remodeling in HGPS mice and suggest that Lgals3bp may represent a potential therapeutic target for aortic pathology in HGPS." (PMID 41209003, 2025).
pulmonary hypertension (1 paper, 2025). Increased pressure within the pulmonary circulation due to lung or heart disorder. "First, the relatively small sample size may limit the generalizability of our findings to the broader IPAH population, and the role of LGALS3BP in other types of pulmonary hypertension remains unknown." (PMID 41308656, 2025).
rectal cancer (1 paper, 2015). A primary or metastatic malignant neoplasm that affects the rectum. "The biomarker signature was comprised of seven proteins (CADM1, LGALS3BP, HYOU1, FN1, VTN, LRG1, and MRC2) (Fig4A) that could predict the localization of rectal tumors especially well (86% of subjects with rectal cancer)." (PMID 26253080, 2015).
renal carcinoma (1 paper, 2024). A carcinoma arising from the epithelium of the renal parenchyma or the renal pelvis. "The correlation between LGALS3BP and various tumor functional states showed that renal cancer is associated with multiple biological phenotypes." (PMID 38393692, 2024). "Furthermore, we determined that LGALS3BP is significantly associated with angiogenesis, stemness and proliferation in renal cancer." (PMID 38393692, 2024). "Second, we did not continue to explore the related pathways of LGALS3BP in renal cancer due to time issues." (PMID 38393692, 2024).
rheumatoid arthritis (1 paper, 2013). A chronic, systemic autoimmune disorder characterized by inflammation in the synovial membranes and articular surfaces. "Galectin-3 and galectin-3 binding protein, LGALS3BP were elevated in rheumatoid synovial fluid, while galectin-3 was elevated in sera of rheumatoid arthritis patients." (PMID 23826184, 2013).
Sepsis (1 paper, 2021). Sepsis is defined as life-threatening organ dysfunction caused by a dysregulated host response to infection. "Strikingly, LGALS3BP was among the most elevated proteins when compared to sepsis ICU patients." (PMID 34099652, 2021).